IL5 (interleukin 5)
Diseases named in the same sentence as IL5 in open-access papers (continued):
Sharing a sentence is not in itself a finding about the gene and the disease.
eosinophilic gastroenteritis (9 papers, 2012 to 2025). "This activation subsequently results in the production of interleukin-5, which plays a crucial role in the pathogenesis of eosinophilic gastroenteritis." (PMID 40514730, 2025). "Transcriptomic analysis of gastric biopsies obtained from patients with eosinophilic gastroenteritis reveals activation of the Th2 cytokine signaling pathways IL-4, IL-5, and IL-13." (PMID 31730503, 2019). "In clinical studies increased secretion of IL-4, IL-5 and IL-13 by peripheral blood T cells has been reported in patients with eosinophilic gastroenteritis." (PMID 27840774, 2015). "Eosinophilic gastroenteritis (EGE) is a rare disease that is characterized by eosinophil infiltration of the gastrointestinal tract due to the release of cytokines, such as interleukin-5 (IL-5), which is associated with eosinophil differentiation and proliferation." (PMID 40514730, 2025). "In addition, the use of monoclonal antibodies against IgE and IL5 such as omalizumab and mepolizumab, respectively, has shown promising results in the treatment of patients with eosinophilic gastroenteritis in clinical trials." (PMID 23346427, 2012). "Elevated IL5 has been reported in ME/CFS plasma and many inflammatory conditions like eosinophilic gastroenteritis, eosinophilic dermatitis, and allergic reactions." (PMID 38650940, 2024). "Anti-interleukin 5 antibodies have not been studied in eosinophilic gastroenteritis." (PMID 34208479, 2021).
fibrosis (9 papers, 2012 to 2024). the formation of excess fibrous connective tissue in an organ or tissue in a reparative or reactive process. "Enhance the secretion of IL-5 and IL-13 which can cause pulmonary inflammation and fibrosis." (PMID 34707601, 2021). "Under an interventional approach, LASSBio-448 reversed ongoing lung eosinophilic infiltration, mucus exacerbation, peribronchiolar fibrosis and AHR by allergen provocation, in a mechanism clearly associated with blockade of pro-inflammatory mediators such as IL-4, IL-5, IL-13 and eotaxin-2." (PMID 27695125, 2016). "We first evaluated the frequency of T CD4+ lymphocytes expressing IL-4, IL-5, and IL-13 after stimulation with SEA, since these cytokines are the main molecules involved in the pathogenesis of periportal fibrosis related to Schistosoma mansoni infection." (PMID 33692784, 2021). "There was no impact of liver steatosis on IL-4, IL-5, IL-10 and IL-22 levels in patients with mild fibrosis." (PMID 39200991, 2024). "The levels of IL-5 in response to SEA were higher in individuals with moderate to severe fibrosis (310.9 pg/mL) compared to individuals without fibrosis (36.8 pg/mL; P = 0.0418)." (PMID 23320145, 2012). "During CHC treatment, patients with SLD had distinct cytokine and growth factor kinetics, with SLD being the main source of variation in several cytokines (IL-5, IL-9, IL-10, IL-13, IL-17A, IL-22) and growth factors (EGF, VEGF and ANG), and it seems this was independent of fibrosis stage." (PMID 39200991, 2024). "Levels of IL-5 in supernatants of SEA-stimulated PBMCs were higher in cultures of individuals with moderate to severe periportal fibrosis, when compared to the group without fibrosis." (PMID 23320145, 2012).
Pruritus (9 papers, 2016 to 2025). Pruritus is an itch or a sensation that makes a person want to scratch. "The advanced stages of CTCL, with typical severe pruritus, shift toward a predominant Th2-cell microenvironment releasing cytokines such as IL-4, IL-5, or IL-31 that have gained attention in other itching inflammatory disorders." (PMID 37874473, 2023). "IL-4, IL-5, and IL-31 cytokines are relevant for pruritus and could be targets for therapeutic interventions." (PMID 37874473, 2023). "Th-2 profile cytokines, such as IL-4, IL-5 and IL-13, play a significant role in the pathogenesis of the disease by switching the immunoglobulin class to IgE and stimulating afferent neurons via IL-4Rα, thereby promoting pruritus." (PMID 34948183, 2021). "IL-4 and IL-5 as key cytokines in the Th2 axis are consistent with the findings of Mast cells in HS41, as well as the pruritus, which is frequently reported by patients." (PMID 30828428, 2018).
T-cell lymphoma (9 papers, 2013 to 2025). "T-cell lymphoma remains a rare but important cause of secondary hypereosinophilia, typically mediated by cytokines such as interleukin-5, which stimulate eosinophil proliferation and activation." (PMID 40846362, 2025). "This subtype is associated with clonal proliferation of IL-5-secreting aberrant T-cells and frequently has skin lesions, lymphadenopathy, and a risk of progression to T-cell lymphoma." (PMID 40926948, 2025). "In secondary or reactive HE, the expansion of eosinophils is a direct result of cytokine overproduction (e.g., IL-5) that can often occur in parasitic infections, solid tumors, T-cell lymphomas, and some connective tissue diseases." (PMID 38611061, 2024). "However, 10 months postadmission, CD4+ T-cell lymphoma, which can produce IL-5, was detected in the nasopharynx and oropharynx." (PMID 32280790, 2019).
urticaria (9 papers, 2010 to 2025). A vascular reaction of the skin characterized by erythema and wheal formation due to localized increase of vascular permeability. "Meanwhile, cutaneous reactions including urticaria, pruritus, and rashes could potentially be linked to listed hypersensitivity reactions to anti-IL-5 medications." (PMID 38308249, 2024). "The unexpected finding of preventing re-occurring seasonal urticaria in horses when targeting self-IL-5 using the eIL-5-CuMV-TT vaccine led to the recruitment of horses affected by recurrent urticaria in the absence of clinical signs of IBH." (PMID 38932291, 2024). "IL-5 was significantly increased in both urticaria-affected samples when compared to healthy samples." (PMID 38932291, 2024). "Following the second vaccination onwards using the IL-5-CuMV-TT, the clinical signs of urticaria disappeared." (PMID 38932291, 2024). "In patients showing urticaria, there is a positive correlation of IL-4 with IL-5, while that of IL-5 with IL-10." (PMID 20616938, 2010). "In phenotypic clusters of NERD, subtype 4 patients (NERD with urticaria) would need omalizumab as an effective option, which can inhibit activated basophils and mast cells, the key elements of NERD and urticaria; subtype 2 patients with severe eosinophilia may need anti-IL-5 as a first option." (PMID 32848759, 2020).
airway allergy (8 papers, 2009 to 2024). "Indeed, the coexpression of Ccl11 and Ccl24,45 or IL-5 and Ccl24,46 correlates with persistent airway eosinophilia in mice with severe airway allergy." (PMID 27484038, 2017). "The TIGIT+ ILC2s have low proliferative activity and low mRNA expression of Il5 and Il13, indicating that TIGIT+ IL-10+ exhausted-like ILC2s can be induced by severe acute and chronic airway allergy even in mice with intact Runx protein function." (PMID 38788198, 2024). "In the murine model of airway allergy, IL-10-producing ILC2s produce high levels of IL-5 and IL-13 compared with non-IL-10 producers." (PMID 38788198, 2024).
allergic bronchopulmonary aspergillosis (8 papers, 2022 to 2026). Allergic bronchopulmonary aspergillosis (ABPA) is a rare immunologic pulmonary disorder caused by hypersensitivity to Aspergillus fumigatus, clinically manifesting with poorly controlled asthma and recurrent pulmonary infiltrates. "In mucus-predominant allergic bronchopulmonary aspergillosis/ABPM with high FeNO/IgE levels after anti-IL-5 therapy, phenotype- and biomarker-guided sequencing of anti-TSLP antibodies may be considered." (PMID 41487819, 2025). "A pediatric patient with allergic bronchopulmonary mycosis with high-attenuation mucus and no fungal sensitization achieved remission with anti–IL-5 therapy, highlighting the diagnostic value of high-attenuation mucus and the role of eosinophilic inflammation in non–IgE-dominant airway disease." (PMID 41459437, 2026). "For example, allergic bronchopulmonary aspergillosis (ABPA) is characterized by Th2 and Th9 cell-type immunity and involves interleukin (IL)-4, IL-5, IL-13, and IL-10." (PMID 38667922, 2024).
anaphylaxis (8 papers, 2017 to 2025). An acute hypersensitivity reaction that occurs from exposure to an allergen. "Cytokines, such as the tumor necrosis factor-α, interleukin (IL)-4, IL-5, and IL-10, act as the contributing mediators in the development of various anaphylaxis symptoms." (PMID 34169047, 2021). "For example, peanut allergen-specific IL-5+ Th2 cells were found in EGID, whereas in peanut anaphylaxis, the peanut-specific Th2 response was almost entirely IL-5− Th2." (PMID 29057225, 2017). "However, Th2 cytokines such as IL-4, IL-5, and IL-13 are thought to promote allergic reactions including eosinophil infiltration and IgE production, which induce Th2-dependent antibodies and systemic anaphylaxis." (PMID 36499554, 2022). "There were no severe adverse events, including episodes of anaphylaxis, during treatment with anti-IL-5/IL-5Rα mAbs." (PMID 37015988, 2023).
chronic sinusitis (8 papers, 2009 to 2025). "A comprehensive analysis of clinical data elucidated that the incidence rates of URTI, nasopharyngitis, and sinusitis were commensurate or less in the anti-IL-5 treated group relative to the placebo cohort, subject to comparable relative risks across each therapeutic subgroup." (PMID 38308249, 2024). "Meanwhile, acute sinusitis demonstrated a diminished risk in both benralizumab and reslizumab groups, and was not noted among the foremost 100 AEs for any anti-IL-5 drugs within post-marketing documentation." (PMID 38308249, 2024).
colorectal cancer (8 papers, 2020 to 2025). A primary or metastatic malignant neoplasm that affects the colon or rectum. "The IVW method was employed to examine the association between eosinophils regulated by gene IL-4, IL-5, IL-13, IL-4R, and IL-5RA and the risk of colorectal cancer and skin malignancies." (PMID 39181688, 2024). "The findings derived from the IVW analysis indicated that the level of the inflammatory factor interleukin-5 (IL-5) (OR = 0.92, 95% CI = 0.84–0.99, P = .049) may be negatively correlated with the risk of colorectal cancer." (PMID 41239614, 2025). "The finding of a correlation between Prevotella and the cytokines IL-5, IL-9 and IL-17A in the tumour microenvironment in colorectal cancer confirms a bidirectional interference between the host immune response and microbiota." (PMID 36407282, 2023). "IL-4, IL-5, and IL-13 are overexpressed in colorectal cancer (CRC)." (PMID 41155334, 2025). "The analysis revealed a negative correlation between eosinophils regulated by IL-4, IL-5, and IL-13 and the risk of colorectal cancer (P < 0.05)." (PMID 39181688, 2024). "Some authors reported that colorectal cancer could have eosinophilic infiltration, and that colorectal cancer had the potential for expression of various chemokines, such as interleukin (IL)-2, IL-3, IL-5, CCL (CC chemokine ligand) 11, or CCL24, that trigger eosinophil development and migration." (PMID 33109117, 2020). "Another study reported that the administration of IL-5 induced MPE formation in syngeneic models of lung adenocarcinoma and colorectal cancer." (PMID 37762343, 2023). "The presence of a Th2 gene signature, which includes IL-4, IL-5, and IL-13, in human colorectal cancer does not appear to have prognostic significance." (PMID 41239618, 2025).
filariasis (8 papers, 2006 to 2024). "Hypo-responsive Th2 cells in both schistosomiasis and filariasis show an intrinsically-impaired ability to produce Th2 cytokines (IL-4, IL-5, IL-10, and IL-13) and to proliferate, both in the presence of antigen and mitogen." (PMID 31815932, 2019). "Mixed Th1/Th2 responses are seen in human filariasis patients, and IL-5 and IFN-γ synergise to kill L. sigmodontis parasites." (PMID 31815932, 2019). "More recently, a synergism between the Th1 (IFN-γ) and Th2 (IL-5) cytokines has been observed in murine filariasis, leading to the containment of infections." (PMID 16542426, 2006). "IL-5 has been demonstrated directly to be essential for protection induced by irradiated L3 larvae and for resolution of primary infection in a fully permissive murine filariasis." (PMID 29892388, 2018). "Interestingly, this reflects studies performed with the murine model of filariasis which have revealed that in the absence of IL-5 infected mice present higher and longer microfilaremic burdens when compared to wildtype strains." (PMID 22509424, 2012).
lupus (8 papers, 2014 to 2025). "In addition, IL-2 expanded the IL-13-producing lupus CD8+ T cells that also expressed IL-5 and IFN-γ in association with STAT6 phosphorylation and GATA-3 expression, but not with STAT5 phosphorylation." (PMID 33763079, 2021). "Estrogens generally enhance humoral autoimmunity and stimulate the T-cell response typical of lupus, leading to increased production of cytokines such as IL-4, IL-5, IL-10, and IL-13." (PMID 40283389, 2025). "It should be noted that IL-2 and IL-5 were reportedly detected, at the transcriptome level, in keratinocytes from healthy and lupus human skin in the minority of individuals." (PMID 32218380, 2020). "Purified human CD4+ T cells stimulated with anti-CD3 and anti-CD28 antibodies exhibited robust production of lupus-related pro-inflammatory cytokines (e.g., IFN-γ, TNF-α, IL-5, and IL-6) upon anti-CD3/CD28 beads stimulation." (PMID 39551768, 2024). "On the other hand, IL-2 expanded IL-13-producing CD8+ T cells that also expressed IL-5 and IFN-γ in lupus patients via a signaling pathway likely involving the activation of STAT6-GATA-3 axis, but not STAT5." (PMID 33763079, 2021). "Our data collectively suggests that IL-2 induces IL-13, IL-5, and IFN-γ expression in lupus CD8+ T cells via STAT6-GATA-3 dependent mechanisms in contrast to the Treg differentiation in which IL-2-STAT5 axis plays a more essential role." (PMID 33763079, 2021).
metabolic syndrome (8 papers, 2018 to 2025). A cluster of metabolic risk factors for CARDIOVASCULAR DISEASES and TYPE 2 DIABETES MELLITUS. "Previous studies have shown that metabolic syndrome is exacerbated in IL-5 or IL-13 deficient mice that were placed on a HFD." (PMID 32948777, 2020). "In parallel, metabolic syndrome has also been shown to independently increase postoperative recurrence risk, accompanied by elevated eosinophil counts and enhanced IL-5 and IL-17A expression, with recurrence risk rising proportionally with the number of metabolic syndrome components." (PMID 41011011, 2025). "Both population studies found that exposure to SO42− affected levels of IL-1β, IL-5, IL-7, IL-12, and IFN-γ, increasing the risk of metabolic syndrome, suggesting that SO42− affects systemic inflammation and metabolic disease." (PMID 39195631, 2024). "Similarly, in absence of IL-5 or IL-13, metabolic syndrome is exacerbated in mice fed a HFD." (PMID 30755607, 2019).
Alzheimer disease (7 papers, 2018 to 2025). A progressive, neurodegenerative disease characterized by loss of function and death of nerve cells in several areas of the brain leading to loss of cognitive function such as memory and language. "In Alzheimer’s disease, IL-5 exhibits a protective role by decreasing tau protein hyperphosphorylation and inhibiting cell apoptosis." (PMID 40563358, 2025). "In Alzheimer’s disease, IL-5 demonstrates a protective function by reducing tau protein hyperphosphorylation and preventing cell apoptosis." (PMID 38612591, 2024). "IL-5 was shown to enhance cognitive function, specifically spatial recognition, in mouse models of Alzheimer’s disease." (PMID 37429945, 2023). "In a mouse model of Alzheimer’s disease (3xTg-AD mice), defects in meningeal ILC2s, including a reduction in cell number and functional deficits in IL-5 production, were identified." (PMID 37429945, 2023). "Multiple brain cytokines were elevated in Alzheimer’s disease and vascular dementia: IL-15 and IL-17A were maximally elevated in end-stage Alzheimer’s disease (Braak tangle stage V–VI) whereas IL-2, IL-5, IL12p40 and IL-16 were highest in intermediate Braak tangle stage III–IV disease." (PMID 33723589, 2021). "It has recently been shown in Alzheimer’s disease that IL-5 blocks the apoptosis of neural cells." (PMID 32209102, 2020). "For many cytokines, (IL-5, IL-2, IL-12p40 and IL-16), however, the level was highest in BSIII–IV disease, suggesting perhaps that the deleterious effects of systemic infection on the brain are likely to be maximal at an early to intermediate stage of Alzheimer’s disease." (PMID 33723589, 2021).